FSTL1 (follistatin like 1)
Diseases named in the same sentence as FSTL1 in open-access papers (continued):
Sharing a sentence is not in itself a finding about the gene and the disease.
rheumatoid arthritis (16 papers, 2011 to 2024). A chronic, systemic autoimmune disorder characterized by inflammation in the synovial membranes and articular surfaces. "Besides, FSTL1 is also associated with rheumatoid arthritis and cardiovascular diseases." (PMID 32188476, 2020). "At the same time, the concentration of FSTL1 in the biological fluids of patients with rheumatoid arthritis is positively correlated with the severity of the disease." (PMID 34440203, 2021). "High FSTL1 levels are found in many systemic autoimmune diseases, such as rheumatoid arthritis, osteoarthritis, and Sjogren’s syndrome." (PMID 34440203, 2021). "In rheumatoid arthritis and osteoarthritis, FSTL1 exacerbates inflammation by increasing the expression of inflammatory factors and promoting synovial proliferation by activating the NF-κB signaling pathway." (PMID 33936382, 2021). "FSTL1 was first cloned in 1988 from the synovial tissues of patients with rheumatoid arthritis after it was detected in the serum and synovial fluid of patients with the disease." (PMID 33292276, 2020). "Follistatin-like 1 (FSTL1) is a glycoprotein with homology to osteonectin and its expression is associated with systemic inflammatory diseases including rheumatoid arthritis, lupus and ulcerative colitis." (PMID 29760587, 2018). "FSTL1 is related to the pathogenesis of human inflammatory and autoimmune diseases, including osteoarthritis, rheumatoid arthritis, reactive arthritis, ulcerative colitis, systemic lupus erythematosus." (PMID 28498809, 2017). "Follistatin-like 1 (FSTL1) was identified as a novel pro-inflammatory protein showing high-level expression in rheumatoid arthritis." (PMID 26716515, 2016). "And some groups identified FSTL1 as a new proinflammatory mediator that contributes to rheumatoid arthritis by promoting the expression of TNFα, IL-1β, IL-6 and IL-8, as well as by enhancing the interferon-γ (IFN-γ) signaling pathway in a mouse model." (PMID 25888873, 2015). "Previous studies revealed a substantial connection between the FSTL1 level and severity of rheumatoid arthritis." (PMID 25888873, 2015). "FSTL1 was originally cloned from synovial tissue of rheumatoid arthritis and has been identified as a novel proinflammatory cytokine." (PMID 24347831, 2013). "FSTL1 is overexpressed in synovial tissue of rheumatoid arthritis, and its serum levels are significantly elevated in patients with systemic inflammatory diseases, such as rheumatoid arthritis, ulcerative colitis, and systemic lupus erythematosus." (PMID 24347831, 2013). "In addition, FSTL1 acts as an autoantigen in patients with rheumatoid arthritis by inhibiting IL6 and producing IL17 to play cardioprotective roles in several cardiovascular diseases." (PMID 33292276, 2020). "Serum FSTL1 levels are notably increased in rheumatoid arthritis and osteoarthritis patients." (PMID 28498809, 2017). "High serum concentrations of FSTL1 are found in many SADs, such as rheumatoid arthritis (RA), in particular juvenile RA with systemic onset, osteoarthritis (OA), and Sjögren’s syndrome." (PMID 29594389, 2018). "The present study is aimed at assessing FSTL1 levels in systemic autoimmune diseases and correlating them with disease activity in patients with rheumatoid arthritis (RA)." (PMID 21303509, 2011). "miR-27a, which is downregulated in individuals with rheumatoid arthritis, inhibits the migration and infiltration of FLS via targeting follistatin-like protein 1 (FSTL1)." (PMID 39530095, 2024). "FSTL1 induced MMP3 and MMP13 gene expression in rheumatoid arthritis synoviocytes requiring MAPK, JAK/STAT3 and NF-κB pathways." (PMID 36497076, 2022).
Arthritis (14 papers, 2011 to 2024). Inflammation of a joint. "Another potential biomarker is FSTL-1, a protein produced by cells of mesenchymal origin that is suggested to be a mediator of innate immune pathways that underlie arthritis in sJIA." (PMID 26634252, 2015). "In vivo, FSTL1 was reported to exacerbate collagen-induced arthritis, associated with enhanced expression of inflammatory cytokines." (PMID 24347831, 2013). "Follistatin-like protein 1 (FSTL1) is a secreted glycoprotein that has been implicated in arthritis pathogenesis in a mouse model." (PMID 22117761, 2011). "Follistatin-like protein 1 (FSTL1) is a proinflammation mediator implicated in arthritis in rodent animal models." (PMID 21303509, 2011). "Overexpression of FSTL1 in macrophages and fibroblasts augments the activity of proinflammatory cytokines, including interleukin (IL)-1β, tumor necrosis factor α (TNFα), and IL-6 and causes severe arthritis in the normal mouse." (PMID 21303509, 2011). "High circulating FSTL1 levels in RA patients might possibly cause deterioration in patients with arthritis by promoting production of proinflammatory cytokines and chemokines in arthritic joints." (PMID 21303509, 2011). "An increase in the expression of FSTL1 induces arthritis and suppresses the production of chemokine-10 (CXCL10) and interferon-gamma (IFN-γ) in arthritic joints." (PMID 33776572, 2021). "FSTL1 is thus playing a crucial role in arthritis by inducing the IFN-γ signaling pathway and stimulating the molecular and cellular mechanism of innate and adaptive immune responses." (PMID 33776572, 2021). "In a mouse arthritis model, FSTL-1 significantly reduced the expression of IL-6 and MMP-13, thereby reducing joint destruction and synovial inflammation." (PMID 33936382, 2021). "FSTL1 has been identified as a novel proinflammatory protein and systemic administration of adenoviral vectors expressing Fstl1 (Ad-Fstl1) to mice induced expression of proinflammatory cytokines in liver and exacerbated collagen-induced arthritis." (PMID 32933544, 2020). "Increased expression of Fstl1 in a chronic but not in an acute mouse model of asthma is in line with previously reported results suggesting different roles of FSTL1 during acute and chronic inflammation in arthritis." (PMID 29594389, 2018). "In the CAIA mouse model, an increase in Fstl1 expression is observed during early stages of arthritis." (PMID 29594389, 2018). "In CIA mice, Ad-mFstl1 exacerbates severity of arthritis, while administration of anti-mFstl1 IgG neutralizes endogenous Fstl1 and reduces the severity of disease." (PMID 29594389, 2018). "This closely resembles the affects reported in arthritis, pointing to a role of FSTL1 in the regulation of the balance of pro- and anti-inflammatory cytokines." (PMID 29594389, 2018). "More importantly, many studies have demonstrated that FSTL1 upregulates proinflammatory mediators in the pathology of arthritis and serum levels of FSTL1 correlating with severity of arthritis." (PMID 28845090, 2017). "In contrast, Fstl1 promotes collagen-induced arthritis by enhancing expression of pro-inflammatory cytokines." (PMID 27145224, 2016). "Fstl1 is reported to ameliorate joint inflammation in a mouse model of arthritis induced by anti-type II collagen antibody and lipopolysaccharide." (PMID 27145224, 2016). "Like many inflammatory factors (such as interleukin-17 (IL-17)), FSTL1 has ‘dual power’ to exacerbate arthritis." (PMID 25888873, 2015). "And a connection between cytokine/chemokine level and FSTL1 expression has been established in mice arthritis models." (PMID 25888873, 2015). "Previous studies showed that FSTL1 expression correlates with severity of arthritis both in OA patients and mice models." (PMID 25888873, 2015). "Adenovirus-mediated administration of FSTL1 to mice exacerbated collagen-induced arthritis, while its neutralization with specific antibody was ameliorative." (PMID 24347831, 2013).
Arthritis (continued). "As expected, a number of altered proteins identified have links to arthritis, including Mmp-2, TGFβ, Fstl1, and Hp." (PMID 21589862, 2011). "FSTL1 neutralization was shown to ameliorate arthritis by inhibiting production of interferon (IFN)-γ and chemokine (C-X-C motif) ligand 10 in arthritic joints of CIA mice." (PMID 21303509, 2011). "Another possibility is that FSTL1 promotes arthritis by increasing neovascularization of inflammatory synovium." (PMID 21303509, 2011). "FSTL1 plays an immunomodulatory role in heart allograft transplantation and ameliorates arthritis in mouse models." (PMID 21303509, 2011). "Previous reports indicate that FSTL1 ameliorates arthritis by inhibiting the production of proinflammatory mediators." (PMID 22117761, 2011). "Furthermore, it was reported that FSTL1 contributes to arthritis as a proinflammatory mediator by enhancing the IFN-γ signaling pathway in a collagen-induced arthritis (CIA) mouse model." (PMID 25888873, 2015). "Although the functions of FSTL1 at the molecular level remain largely unknown, several reports indicate that FSTL1 is involved in arthritis pathogenesis." (PMID 22117761, 2011). "Therefore, it could be that FSTL1 plays different roles in varied cell and disease settings or at different stages in the pathogenesis and progression of arthritis." (PMID 21303509, 2011). "Interestingly, the FSTL1 expression was also stronger in the endothelial cells (ECs) of the OA samples than in the controls, suggesting a possible role in angiogenesis in arthritis." (PMID 22117761, 2011). "Therefore, increased FSTL1 levels in RA could aggravate arthritis by FSTL1-mediated neovascularization in RA STs." (PMID 21303509, 2011). "Follistatin-like 1 (FSTL1) exhibits altered expression in various health conditions, including cardiovascular diseases, arthritis, and cancer." (PMID 38605354, 2024). "Follistatin-like 1 (FSTL1) is a secreted glycoprotein displaying expression changes during development and disease, among which cardiovascular disease, cancer, and arthritis." (PMID 29594389, 2018). "For these RA patients with lack of systemic arthritis symptoms, we could not exclude the possibility that FLS stimulated continually by proinflammatory mediators increased FSTL1 concentrations in STs and then released FSTL1 into serum." (PMID 21303509, 2011).
gastric cancer (13 papers, 2019 to 2026). A primary or metastatic malignant neoplasm involving the stomach. "In the realm of cancer, FSTL1 has been implicated in gastric cancer progression by promoting cell proliferation and metastasis through the activation of the AKT signaling pathway, which is indicative of a poor prognosis." (PMID 38605354, 2024). "Previous studies have indicated COL5A1’s role in gastric cancer progression through acting as a ceRNA for miR-137-3p to promote FSTL1 expression and its association with ovarian cancer progression, taxol resistance, and immune cell infiltration in the tumor environment." (PMID 39850883, 2024). "In the field of oncology research, studies have shown that FSTL1 plays an important role in promoting tumor progression in a variety of tumors, including hepatocellular carcinoma, gastric cancer, colorectal cancer, osteosarcoma and nasopharyngeal carcinoma." (PMID 38605354, 2024). "Specifically, FSTL1 was positively correlated with the stromal, immune, and ESTIMATE scores, suggesting that the expression of FSTL1 was negatively correlated with the purity of gastric cancer, while a low tumor purity often indicates a poor prognosis." (PMID 35805015, 2022). "FSTL1 is upregulated in many solid tumor cells including glioma, gastric cancer, and hepatocellular carcinoma, and inhibiting the expression of FSTL1 can effectively reduce various malignant biological behaviors of cancer cells." (PMID 36268275, 2022). "Other highly correlated genes that have previously been implicated in gastric cancer included CDH11, MSRB3 and FSTL1." (PMID 35406381, 2022). "In gastric cancer, it was reported that FSTL1 knockdown promotes apoptosis via the STAT6 signaling pathway." (PMID 34425560, 2021). "Knockdown of COL5A1 inhibited the proliferation, invasion, and migration of gastric cancer cells, which could be rescued by the miR-137-3p inhibitor or overexpression of FSTL1." (PMID 35805015, 2022). "I with a logFC >1, we generated a gene signature of iGC stage progression (intestinal-type gastric cancer progression signature - iGCPS), composed of APOD, COL1A2, GEM, FSTL1, LUM and SPARC." (PMID 39563861, 2024). "In recent years, some researchers have pointed out that immune-related genes, Follistatin-like 1 (FSTL1), immune T cell subgroup, preoperative neutrophil-lymphocyte ratio (NLR), and platelet-lymphocyte ratio (PLR) may be significantly associated with the prognosis of gastric cancer." (PMID 35220959, 2022). "Follistatin-like 1 (FSTL1), miR-23b, ETS1, and TCF4 have all been reported to be prognostic biomarkers for gastric cancer patients, mainly involved in tumor progression and tumor immunity." (PMID 34980151, 2022). "However, the effect of FSTL1 on the prognosis and immune infiltration of gastric cancer (GC) remains to be elucidated." (PMID 33292276, 2020). "In line with these facts, inhibition of autophagy reduces FSTL1 (follistatin like 1)-induced EMT in human bronchial epithelial cells, whereas ATG4A overexpression significantly promotes EMT in gastric cancer cells." (PMID 30782064, 2019).
colorectal cancer (12 papers, 2018 to 2024). A primary or metastatic malignant neoplasm that affects the colon or rectum. "Likewise, knockdown of FSTL1 has been reported to inhibit cell proliferation and migration of colorectal cancer cells, thus representing a potential therapeutic target for pterygia." (PMID 35174178, 2021). "For example, FSTL1 has been found to promote tumor inhibition in breast cancer and clear-cell renal cell carcinoma; however, it is a poor prognostic indicator of colorectal cancer, esophageal squamous cell carcinoma, and hepatocellular carcinoma." (PMID 33292276, 2020). "Here, we investigated the expression and functional role of FSTL1 in colorectal cancer (CRC)." (PMID 30131854, 2018). "Previous study has reported that FSTL1 binds to VIM and facilitates colorectal cancer metastasis through activating the focal adhesion signalling pathway." (PMID 31772671, 2019). "However, the role of FSTL1 in colorectal cancer (CRC) remains unclear." (PMID 29844309, 2018). "Moreover, FSTL-1 was shown to promote metastasis and chemo-resistance in esophageal squamous cell carcinoma through NFκB-BMP signaling crosstalk and to promote colorectal cancer metastasis via activating the focal adhesion signaling pathway." (PMID 33514403, 2021). "So far, the role of FSTL1 in colorectal cancer progression and metastasis has not been well characterised." (PMID 29844309, 2018).
lung carcinoma (12 papers, 2016 to 2025). "Since low FSTL1 expression is associated with smoking history, we further investigated the effect of nicotine on lung cancer cells." (PMID 28852126, 2017). "An increase in histone H3 phosphorylation (at Ser10), another hallmark of mitosis, indicated that the knockdown of FSTL1 in lung cancer cells stimulated a mitotic arrest." (PMID 26716515, 2016). "Recent results from Fstl1-deficient mice, which displayed impaired lung development and alveolar maturation, motivated us to study the relationship between FSTL1 and lung cancer." (PMID 26716515, 2016). "However, the essential role of FSTL1 in mouse lung development as shown by FSTL1-deficient mice makes it plausible to study the role of FSTL1 in lung cancer cells." (PMID 26716515, 2016). "In a condition characterized by chronic intermittent hypoxia, such as OSA, FSTL1 levels decline severely in lung cancer tissue, which aggravates oxidative stress and inflammatory responses." (PMID 41458545, 2025). "As we previously discovered, FSTL1 can regulate the progression of lung cancer by interacting with secreted phosphoprotein 1 (SPP1), and the distribution of molecular molecules associated with BMP and TGF‐β signalling is the opposite." (PMID 36807490, 2023). "Here, we examined the effects of FSTL1 on cellular proliferation and cell cycle checkpoints in lung cancer cells." (PMID 26716515, 2016). "FSTL1 plays the important roles in cellular proliferation and apoptosis in lung cancer cells, and thus can be a new target for lung cancer treatment." (PMID 26716515, 2016). "This is the first report to suggest the potential therapeutic effect of FSTL1 blockade in lung cancer." (PMID 26716515, 2016). "FSTL1 inhibition induced the cellular portion of G2/M phase in human lung cancer cells via the accumulation of regulators of the transition through the G2/M phase, including the cyclin-dependent kinase 1 (Cdk1)-cyclin B1 complex." (PMID 26716515, 2016). "Taken together, our results suggest that FSTL1 plays an important role in maintaining cell cycle transitions and its inhibition promotes apoptotic event in lung cancer." (PMID 26716515, 2016). "In this study, we investigated the effects of FSTL1 on cell cycle and apoptosis in lung cancer cells." (PMID 26716515, 2016). "They found that FSTL1 prevents the nicotine-induced proliferation of lung cancer cell lines." (PMID 36756161, 2023). "Likewise, it has been demonstrated that FSTL1 can suppress the proliferation of nicotine-induced lung cancer cells, and C1QC has proven valuable for the diagnosis of skin cutaneous melanoma with improved overall survival." (PMID 37775746, 2023). "Our previous analyses of FSTL1 in lung cancer have shown that its location within the cell may have a significant effect on its function." (PMID 36807490, 2023). "Cx43 also suppresses lung cancer cell invasion and metastasis, possibly by acting as a “histone deacetylase inhibitor” affecting the gene expression of several genes, such as by increasing the expression and secretion of FSTL1 (follistatin-like 1)." (PMID 30845770, 2019). "FSTL1 expression inhibits cell growth and invasion of lung cancer cells, and the invasion ability could be blocked by FSTL1 antibody treatment." (PMID 28852126, 2017). "Nicotine-induced proliferation is mediated through ERK/MAPK signaling pathway and FSTL1 may attenuate nicotine-induced proliferation in lung cancer cells." (PMID 28852126, 2017). "Here we showed the FSTL1 inhibition effect in nicotine-induced lung cancer cell proliferation." (PMID 28852126, 2017). "In addition, FSTL1 knockdown resulted in a significant increase in cell death in lung cancer cells as indicated by PARP cleavage determined by western blotting." (PMID 26716515, 2016). "FSTL1 may prevent nicotine-induced lung cancer cell proliferation." (PMID 28852126, 2017). "Indeed, overexpression of FSTL1 suppressed the proliferation ability of lung cancer cells." (PMID 26918942, 2016).
lung carcinoma (continued). "Although other members share this oncogenic potential, some inhibit cancer progression such as FSTL1, which has been recently shown to interact with another MCP called osteopontin to inhibit lung cancer metastasis." (PMID 35869056, 2022). "Frequent decrease of FSTL1 expression in smokers LUAD further indicates its importance and therapeutic potential for lung cancer patients with specific subtypes." (PMID 28852126, 2017). "Thus, FSTL1 could be a potential candidate therapeutic target for lung cancer." (PMID 26716515, 2016). "The expression pattern of FSTL1 is not consistent in lung cancer when we compared several data sets from the Oncomine database." (PMID 26716515, 2016). "Interestingly, FSTL1 attenuated nicotine-induced BEAS2B and lung cancer cell line proliferation." (PMID 28852126, 2017).